ATM (ATM serine/threonine kinase)
Diseases named in the same sentence as ATM in open-access papers (continued):
Sharing a sentence is not in itself a finding about the gene and the disease.
cancer (continued). "Taken together, these results suggest that miR-18a plays an important role in the regulation of ATM and may represent a therapeutic target for cancers and other diseases." (PMID 21980462, 2011). "AT is an autosomal recessive human genetic disease characterized by an increased risk of cancer and caused by a mutation in the Ataxia Telangiectasia Mutated (ATM) gene, leading to a lack of ATM protein." (PMID 20454669, 2010). "Nearly 40% of ATM homozygotes will develop cancer, usually childhood leukaemia or lymphoma." (PMID 21203498, 2010). "There may also be future scope to determine tumour thresholds for ATM for optimum IR control of cancer." (PMID 20678261, 2010). "AT-mutated (ATM) provides the closest genetic link between neurodegeneration and cancer thus far." (PMID 21203498, 2010). "In the present study we used comparative immuno-blotting of the ATM protein to investigate a cohort of cancer patients selected on the basis of their severe adverse reactions to adjuvant radiotherapy and compared these with control patients with no adverse reactions." (PMID 20678261, 2010). "Indeed, it is reported that overexpression of Cdt1 can induce overt re-replication in cancer-derived cell lines, with activation of ATM/ATR checkpoint pathways." (PMID 17042960, 2006). "No family in the study was selected due to sporadic ATM gene mutation analyses of tumour tissue from cancer patients in the general population." (PMID 15942625, 2005). "Translationally, combining ATM inhibitors with DNA-damaging chemotherapies or radiotherapy could potentiate tumor-specific apoptosis by exploiting defective repair pathways often found in cancer cells." (PMID 41557625, 2026). "Moreover, ATM inhibition may represent an effective strategy in cancers with impairment of other DDR genes due to synthetic lethality, a phenomenon known to significantly impact sensitivity to other DDR-directed cancer drugs, such as PARP inhibitors." (PMID 40875525, 2025). "Additionally, given ATM’s critical role in maintaining genomic stability across various tissues, the long-term inhibition of ATM by AZD1390 could potentially disrupt immune function or impair tumor suppression, thereby increasing cancer risk." (PMID 40723779, 2025). "Interestingly, this pathway is distinct from the regulation of mTORC1 by ATM and may be specific to cancer cells." (PMID 40514450, 2025). "Moreover, loss/perturbation of EME1 phenocopies SETD1A loss in the absence of both BRCA1 and ATM and led to the restoration of HR, which was supported by data from cancer cell lines." (PMID 39994444, 2025). "ATM, a DNA repair gene, is associated with various cancers but not previously linked to HCC." (PMID 41146957, 2025). "Gene ontology overrepresentation analysis revealed that specific hub genes in each module may be enriched in specific cancer-related biological processes, such as the ATM pathway and the adaptive immune system, prompting us to further characterize the cancer immunology of DEGs." (PMID 41431699, 2025). "In cancerous cells the same function of ATM might favour tumour growth and cancer cell survival." (PMID 38519707, 2024). "However, most individuals with germline deleterious ATM variants are heterozygous carriers with a 2- to 13-fold increased risk for early-onset cancer development but do not have other features of A-T." (PMID 38203823, 2024). "Likewise, ATR is not as commonly mutated or depleted in cancer cells as has been observed for ATM (TCGA)." (PMID 39456630, 2024).
cancer (continued). "However, the myriad of side effects known to be associated with ATM inhibitors in cancer therapy cannot be ignored, which are caused by the fundamental role of ATM in DNA damage repair signaling." (PMID 38933336, 2024). "Furthermore, BCAC and Cancer Risks Estimates Related to Susceptibility Consortium (CARRIERS), suggested BRCA1, BRCA2, ATM, PALB2, and CHEK2 genes as highly penetrant; both consortiums pinpointed that 10% of BC patients have cancer susceptibility germline mutation." (PMID 38890714, 2024). "However, there is no conclusive evidence that carriers of a pathogenic ATM mutation, who have been diagnosed with cancer, have increased cancer risk secondary to radiation therapy compared with noncarriers." (PMID 39684891, 2024). "Further analysis revealed that our population is enriched for pathogenic variants in ATM, BRCA1, and CDH1 genes and that prevalence of pathogenic variants in the CHEK2 gene is lower in the Slovenian population, when compared to GnomAD non-cancer control population." (PMID 37002323, 2023). "In addition to the clinical potential of targeting APE1 in combinatorial therapies, it has been demonstrated that APE1 nuclease inhibitors induce the SL of cancer cells that are deficient in DNA DSB repair, i.e., BRCA or ataxia telangiectasia mutated (ATM) defective cell models." (PMID 38068959, 2023). "Furthermore, we showed that direct inhibition of ATM phosphorylation is able to reduce OXPHOS levels in oncogene-driven cancer cells and to enhance apoptosis in response to TK inhibitors, thus highlighting the possibility to use ATM inhibitors in combination therapy." (PMID 37932830, 2023). "Therefore, for DSB-tolerant cancer cells with upregulated ATM signaling, combination therapy with an ATMi could make TRT more effective than TRT alone by increasing the number of unrepaired DSBs." (PMID 37514113, 2023). "Therefore, targeting ATR may be a promising strategy to treat cancer-harbored defects in ATM signaling, attracting broad interest in industry and academia." (PMID 37298997, 2023). "Consequently, the absence of normal ATM functioning among the hereditary AT syndrome demonstrates that it leads to pleiotropic clinical syndrome related to the apparently growing risk of cancer and serious allergy to ionizing radiation." (PMID 36873996, 2023). "However, in NKX3.1-expressing cancer cases, the expressional loss of NKX3.1 after androgen deprivation therapy also results in functional loss, leading to deregulated activation of antioxidant response and ATM-mediated DDR mechanisms." (PMID 38155939, 2023). "Furthermore, the phosphorylation of STAT1, a key transcription factor downstream of IFNβ pathway that contributes to the activation of IFN-stimulated genes, was also enhanced upon ATM inhibition in a panel of human and murine cancer cells (BT549, MDA-MB-231, H1299, H157, A549, B16-F10 and MC-38)." (PMID 36778120, 2023). "Notably, the remaining six patients (19.4%) had a personal history of cancers not currently associated with ATM hereditary cancer susceptibility." (PMID 36865800, 2023). "Therefore, ATM suppression would be advantageous in eradicating cancer cells, in particular CSCs, but disadvantageous for normal cells because its function is indispensable in DNA repair, in preserving mitochondrial functionality, and in the selective removal of damaged mitochondria." (PMID 36900267, 2023). "In summary, ATM, as an important node in cell cycle arrest and apoptosis, may reduce radiation-induced resistance to radiotherapy by suppressing the ATM gene, and is thus a successful tactic by which to enhance the therapeutic impacts of cancer treatments and enhance patient prognosis." (PMID 37322433, 2023). "Prior research has suggested that ATR inhibitors may have substantial efficacy in ATM-deficient cancers, yet in Cohort E we do not see strong evidence for activity in cancers with absent/low ATM expression." (PMID 37773077, 2023).
cancer (continued). "Although we did not found a significant association between ATM and PanC, based on this observation an effect of ATM on cancer germline predisposition not independent of BRCA2 might be supposed." (PMID 36717774, 2023). "Moreover, prior study indicates that ATM deficiency activates cGAS/STING through promoting cytoplasmic leakage of mitochondrial DNA, and subsequently induces type I interferon (T1IFN)-mediated innate immune response in certain cancer types 21,22." (PMID 36778120, 2023). "On the other hand, ATM is critical for the control of cellular redox homeostasis, which, if perturbed, may result in cancer through elevated mitochondrial ROS production mediating genomic instability, chronic inflammation, and the development of an active tumor microenvironment." (PMID 37511215, 2023). "The ATM gene encodes the ATM serine/threonine kinase, which has a major role in DNA repair, and the absence of ATM expression leads to genomic instability and cancer predisposition." (PMID 35804819, 2022). "Indeed, the presence of DSBs (likely to be higher in HRD tumors) has been found to upregulate PD-L1 expression in cancer cells, in a process that requires ATM/ATR/Chk1 kinases and is driven by STAT1 and STAT3 signaling, providing a potential explanation for the elevated PD-L1 seen in HRD tumors." (PMID 36362142, 2022). "Despite its key role in homologous recombination repair, also including other factors such as ATM and BRCA1 that are among the top mutated genes in the samples analyzed, it has never been found significantly altered in NENs so far, although its role in cancer development and treatment is emerging." (PMID 35794609, 2022). "The biological consequence of the significant downregulation of ATM and ATR observed in Saos-2/CDDP-resistant variants is a relevant finding that needs to be further explored, since inhibitors against ATR have already been used in clinical trials in other cancers." (PMID 36233089, 2022). "In addition, two ATM mutations were identified in screening-naïve families with no cancer-affected female relatives." (PMID 35892882, 2022). "By comparing genomic and transcriptional profiles, ATM-dependent signaling emerged among the most significant pathways at multiple levels, involving gene variations and miRNA-mediated regulation, thus representing a novel putative druggable pathway in these cancer types." (PMID 35794609, 2022). "However growing evidences also suggest that ATM is also involved in promoting chemo- and radio-resistance to cancer cells which might in turn be the reflection of the dual nature of the autophagic processes that the protein initiates." (PMID 36172166, 2022). "Targeting DNA damage checkpoint kinase, such as ATR/ATM, could be promising for cancer treatment." (PMID 35287310, 2022). "Thus, to potentiate the therapeutic effects of gemcitabine and cisplatin specifically on a molecular level, we focused our attention, in a next step, on the ATM/ATR pathway that contributes to the DNA damage response in cancer and upon various types of chemotherapies, including antimetabolites." (PMID 34439352, 2021).
cancer (continued). "Other critical components of the DDR, including ataxia telangiectasia and Rad3-related (ATR), ataxia telangiectasia mutated (ATM), DNA-dependent protein kinase (DNA-PK), Checkpoint kinase 1 (CHK1), Checkpoint kinase 2 (CHK2) and Wee1 kinase (WEE1), are also promising as targets for fighting cancer." (PMID 34885119, 2021). "Moreover, some efficient treatments, including radiotherapy and immunotherapy, control ferroptosis and promote immunotherapy-activated CD8+ T cells, and radiotherapy-activated ATM can effectively kill cancer cells and prevent cancer cells from escaping immune surveillance." (PMID 34386492, 2021). "Moreover, nonfunctional ATM has been associated with an increased risk for cancer, radiation sensitivity, endocrine disruption, progressive neurodegeneration, premature ageing, and chromosomal instability (most recently reviewed by Shiloh)." (PMID 33868575, 2021). "Moreover, it directly activates ATM signaling in a context of oxidative stress, which may explain the opposing effect in cancer and normal cells." (PMID 34041023, 2021). "Moreover, next generation sequencing (NGS) analysis revealed that ATM is among the most aberrant gene in sporadic cancer (as shown by the COSMIC database), and that loss of heterozygosity in the region of the ATM has been detected in approximately 40% of human sporadic BC." (PMID 34068084, 2021). "Moreover, DADS resisted the activation of the G2/M gene damage checkpoints by relying on Mec1 (ATR) and Tel1 (ATM) to inhibit DNA repair, which could improve the efficacy of DNA damage-based cancer therapies." (PMID 34745287, 2021). "Therefore, cancer cells can use different mechanisms to downregulate ATM." (PMID 34070860, 2021). "Nevertheless, based on our observations and the findings by others, the current working hypothesis is that PARPi such as olapraib may not show significant clinical benefits for cancer patients with loss of ATM protein." (PMID 34320214, 2021). "Several associations of significant HRD-predisposing genes and cancer types in specific populations were previously reported for the same population, for example, BAP1 with BRCA in the ‘White’ and ‘African American/Black’ populations and ATM with STAD in the ‘White’ and ‘Asian’ populations." (PMID 34945758, 2021). "Although ATM is considered as an oncosuppressor gene owing to its role in enhancing chemo-radioresistance of tumor cells, this aberrant protein could potentially be explored as a target for cancer treatment." (PMID 34068084, 2021). "This approach underlines the importance of screening all missense mutations founded in cancer or A-T milder phenotype patients to predict the subtle effects of the reduced ATM activity, which is not easy to predict, and to individuate the right therapy approach." (PMID 34771661, 2021). "ATR inhibition is lethal with numerous cancer-associated changes, including oncogenic stress (oncogenic RAS mutations, MYC and G1/S-specific cyclin-E1 (CCNE1) overexpression), deficiencies in DNA repair (TTP53, BRCA1/2, partner and localizer of BRCA2 (PALB2) and ATM loss) and other defects." (PMID 32316968, 2020). "Having identified the Rad50L1237F mutation as the underlying cause of an extraordinary response to chemotherapy, likely due to its selective inability to activate Tel1/ATM, we reasoned that cancer genomic data could offer a rich source for understanding Mre11 complex functions." (PMID 32187176, 2020). "In the same study, the ATM gene was further analyzed in a cohort of 392 non-BRCA cancer families and showed 1.78% prevalence of mutations in non-BRCA familial BC/OC and a 1.94% frequency in BC, suggesting that testing of this gene in Spanish non-BRCA families should occur." (PMID 31936873, 2020).
cancer (continued). "Altogether, our results demonstrate that HITT plays essential roles in inhibiting the HR pathway by restraining ATM activity and thus may be an effective adjuvant therapy for genotoxic or radiomimetic compounds or a predictive marker for treatment efficiency in cancer." (PMID 32203529, 2020). "However, the association between variants in ATM, mostly known for being associated with a low-intermediate risk of other cancers, and CM risk is not yet clearly established." (PMID 32325837, 2020). "Targeting ATM may be a promising strategy for cancer treatment." (PMID 32201399, 2020). "We also included ATM and PALB2 for research purposes, excluding them from the clinical report, under the assumption that their variants could play a role in families with known cancer associations, that is, CM and PC." (PMID 32325837, 2020). "Thus, the prediction of instinct sensitivity towards ionization therapy based on detecting DSB repair efficiency of cancer cells or monitoring ATM expression might be a promising new strategy for cancer treatment." (PMID 32174787, 2020). "mTOR signaling may promote the survival of cancer cells via enhancing the expression of FANCD2, CHK1 and RRM2 through CDK4/6 while inhibiting ATM, revealing the potential mechanisms of the increased cancer cell growth and proliferation under stressful conditions." (PMID 31285446, 2019). "In addition, our studies provide proof-of-concept for novel potential strategies for senescence prevention through blockade of ATM-associated DNA damage response and/or inhibition of STAT1/STAT3 signaling in effector T cells for clinical immunotherapy against cancer and chronic infections." (PMID 29339767, 2018). "Therefore, the frequent downregulation of ATM in EBV‐positive NPC may partly explain the exceptionally high radio‐sensitivity of this deadly cancer." (PMID 29230817, 2018). "Thus, the SYCE2 expression levels, which vary among cancers, may define the background ATM-mediated DNA repair capacity of each cancer." (PMID 30456351, 2018). "Based on these data, we conclude that regulation of pre-mRNA splicing is important for ATM-dependent DNA damage response while dysregulation of spliceosomal machinery induced by a splicing inhibitor impairs ATM signaling and increases the sensitivity of cancer cells to genotoxic stress." (PMID 29950180, 2018). "Our study showed higher mutation load in patients carrying ATM/RB1 mutations in the combined datasets, suggesting the correlation between DNA repair defect and mutation burden may still be present in sporadic cancers as a result of increased genomic instability through loss of DSB DNA repair." (PMID 29682192, 2018). "As a consequence, the lower BER capacity observed in cells lacking ATM could be one of the contributing factors leading to susceptibility to cancer in A-T individuals." (PMID 28973444, 2017). "Cdc7-Dbf4 kinase also is an excellent target for therapeutic strategies that not only block DNA synthesis at the beginning but also sensitize cancer cells to DNA damage by targeting HSP90/ATR/ATM, which may a promising approach to enhance the therapeutic effect of radiation or chemotherapy." (PMID 29209046, 2017).